AR (androgen receptor)
Diseases named in the same sentence as AR in open-access papers (continued):
Sharing a sentence is not in itself a finding about the gene and the disease.
prostate carcinoma (continued). "The role of the IRE1α/IL-6/AR positive feedback loop in controlling castration-resistant growth of prostate cancer cells suggests that this signaling network could be a prognostic indicator and therapeutic target of CRPC." (PMID 34295814, 2021). "Herein, to our knowledge, we present the first study of a multiplex gene expression biomarker panel in 147 patients with metastatic prostate cancer designed to detect three major mechanisms of resistance to ARSIs in prostate cancer: AR-Vs, AR pathway activation, and NEPC." (PMID 34197212, 2021). "Considering that AR is heavily affected by other PTMs, they could potentially be explored in prostate cancer treatment." (PMID 33572160, 2021). "Furthermore, MYLIP is an E3 ubiquitin-protein ligase whose activity depends on E2 enzymes of the UBE2D family and that was shown to affect AR activity in prostate cancer." (PMID 33572160, 2021). "Notably, we also discuss the mechanisms of lncRNA–miRNA interaction in androgen receptor-independent prostate cancer, such as growth factors, oncogenic signaling pathways, cell cycle dysregulation, and cytokines or other transmembrane proteins." (PMID 35008817, 2021). "AR is phosphorylated at 18 sites by many different enzymes, which influences its stability, nuclear localization, and transcriptional activity, which in turn regulates the prostate cancer cell fate." (PMID 33572160, 2021). "Androgen receptor (AR) is phosphorylated at Ser81 (pS81) in prostate cancer." (PMID 33932081, 2021). "Importantly, GRPR and PSMA expression are both affected by standard of care treatments applied in prostate cancer, including targeting the androgen receptor pathway and taxane-based chemotherapy." (PMID 34830920, 2021). "In this article, we review the physiology of androgen receptor signaling, studies that present different mechanisms of neuroendocrine transformation of prostate cancer, and potential neuroendocrine prostate cancer (NEPC)-specific markers for targeted management." (PMID 33754118, 2021). "PRPF6 activates AR/AR-Vs to promote the progression of hepatocellular cancer and prostate cancer." (PMID 37303939, 2021). "Studies have validated that besides AR, ONRs could be the potential therapeutic targets for prostate cancer, particularly the lethal CRPC progression." (PMID 33750894, 2021). "Both herbs affect androgen receptor–mediated functions in prostate cancer." (PMID 34476412, 2021). "In addition to the AR-dependent pathway above, the AR-independent pathway is also an important mechanism for ASC-J9 to inhibit the proliferation of prostate cancer." (PMID 34295247, 2021). "Additionally, a pool of platelet-derived androgens from these patients was proven to be sufficient to induce androgen receptor signaling in prostate neoplastic cells, leading to the growth of prostate cancer." (PMID 33406783, 2021). "Moreover, ACK1 phosphorylates androgen receptor (AR) at Tyr267 and Try363 to stimulate the progression of prostate cancers." (PMID 33495411, 2021). "In prostate cancer, the glucocorticoid receptor (GR) is a prime suspect for acquired therapy resistance, as resistance to the antiandrogen enzalutamide (Enz) can occur through bypass of androgen receptor (AR) blockade by the glucocorticoid receptor (GR)." (PMID 34412644, 2021). "AR is a ligand-dependent transcription factor that plays a critical role in both normal development of the male phenotype and development and progression of prostate cancer." (PMID 34638309, 2021).
prostate carcinoma (continued). "Therapies that target the androgen receptor axis induce apoptosis in normal prostates and provide temporary relief for advanced disease, yet prostate cancer that acquired androgen independence (so called castration-resistant prostate cancer, CRPC) invariably progresses to lethal disease." (PMID 33668112, 2021). "In addition, a dynamic AR cistron dependent on androgen level was found, which exists in the high AR affinity region of prostate cancer cell lines and tissue samples." (PMID 34976824, 2021). "Previous studies showed that combination treatment with an AR inhibitor (enzalutamide), antibiotic (clofoctol) or a natural product (Nobiletin) promoted the anti-cancer effects of sorafenib in castration-resistant prostate cancer." (PMID 34026624, 2021). "In prostate cells, CHIP ubiquitinates the androgen receptor, a major driver of prostate cancer, and targets it for proteasomal degradation, indicating that CHIP might also be involved in prostate cancer." (PMID 33670160, 2021). "In prostate cancer mouse model, the therapeutic efficiency of Cabozantinib appears to be strongly associated with MET pathway, reducing cancer cell invasion, and this action synergizes with androgen receptor antagonist therapy." (PMID 34745989, 2021). "Since androgens are one of the main driving forces of prostate cancer, other than chemotherapeutic agents such as docetaxel and cabazitaxel, the androgen receptor (AR) and steroid biosynthesizing cytochrome P450 17A1 (CYP17A1) have been the primary targets of PCa treatment." (PMID 34199743, 2021). "Androgen receptor (AR) is critical to the initiation, growth, and progression of prostate cancer." (PMID 33975627, 2021). "That implies that pAKTS473 directly phosphorylates AR at S210/213, as described in prostate cancer." (PMID 34681618, 2021). "To identify factors that selectively bind the agonist conformation of AR, we introduced Flag epitope-tagged wild-type (WT) AR into PC3 prostate cancer cells, treated the cells with an androgen agonist (R1881), and at multiple timepoints (0–24 h), isolated AR by immunoprecipitation (IP)." (PMID 33976187, 2021). "The growth of prostate cancer is controlled by androgen/androgen receptor (AR) axis." (PMID 33390843, 2021). "In conclusion, recent studies using different model systems including transgenic mouse models with PSMA null background have elucidated several distinct mechanisms associating PSMA with survival-related signaling pathways with connections to the androgen receptor (AR) signaling in prostate cancer." (PMID 34067046, 2021). "Understanding how this level of regulation of AR functions is affected by AR activity, by surrounding cellular context, and how it becomes aberrated during prostate cancer development and progression, are questions that can be assessed by utilizing protein interactomics." (PMID 34638309, 2021). "Therefore, our group and others focused on exploring the important regulator of the AR signaling pathway in prostate cancer." (PMID 34685466, 2021). "The information on other natural products such as genistein, celastrol, berberine, honokiol, silymarin, and ginsenosides available in the literature suggests that they may mediate in androgen receptor-based therapy for prostate cancer." (PMID 33807174, 2021). "It is also possible that RAC1 inhibitors may be valuable in treating other diseases, such as AR-positive prostate cancer." (PMID 34373577, 2021). "In prostate cancer, AR is the major driver of disease progression, but it remains unclear how additional genes drive mCRPC through AR-dependent and independent mechanisms." (PMID 34326322, 2021). "This newly identified interaction between SHH-N and AR is one potential mechanism of sustaining androgen-independent growth of prostate cancer cells and could represent a new therapeutic target." (PMID 34290270, 2021).
prostate carcinoma (continued). "In 2015, this group used the same method to analyze 77 CTCs obtained from the peripheral blood of 13 prostate cancer patients and found that gene expression in CTCs was heterogeneous and included androgen receptor (AR) mutants and splicing-related differential expression of isomers." (PMID 34412644, 2021). "Since the 2004 nuclear receptor issue of this journal, there have been tremendous advances in our understanding of AR's functions in prostate cancer, development of new AR-targeting therapies and identification of novel mechanisms of resistance to these hormone therapies." (PMID 34825698, 2021). "As breast and prostate cancers have yielded much evidence that pAKTS473 can phosphorylate AR at S210/213, we examined whether this was also the case in gliomas." (PMID 34681618, 2021). "Active androgen receptor (AR) signaling is central to prostate cancer development and progression." (PMID 34168263, 2021). "A number of anti-androgens, which directly bind to the ligand-binding domain of AR and prevent its activation by ligand, are used to treat prostate cancer as well as other diseases such as polycystic ovarian syndrome, alopecia and are being trialled for breast cancer." (PMID 34328182, 2021). "AR-expressing prostate cancer lines displayed varying levels of NDRG1 pS330." (PMID 33398037, 2021). "In addition to human cancer treatment testimonies, research studies have previously shown that BIRM is effective for prostate cancer by regulating androgen receptor in cellular and animal models." (PMID 34476412, 2021). "Prostate cancer (PC) relies on androgen-receptor (AR) signaling for development and progression." (PMID 34489465, 2021). "In addition, hnRNPK regulates and directly interacts with the androgen receptor translational apparatus in prostate cancer." (PMID 33806648, 2021). "Furthermore, Adiol has recently been shown to stimulate the androgen receptor (AR) in LNCaP prostate cancer cells leading to proliferation." (PMID 34064842, 2021). "However, ATF3 also acts as a tumor suppressor in prostate cancer by blocking pro-survival pathways, such as androgen receptor and AKT pathways, ultimately leading to the inhibition of cell proliferation and invasion." (PMID 34571936, 2021). "MED19 overexpression also did not induce expression of AR-V7, a constitutively active splice variant of AR lacking the ligand binding domain that can drive androgen independence in prostate cancer." (PMID 33513133, 2021). "Moreover, AR targeting impairs DNA double-strand break repair by inhibiting non-homologous end joining, thereby increasing the radiosensitivity of prostate cancer cells." (PMID 35004302, 2021). "AR affects the expression of several kinases and phosphatases, and results from phoshoproteome studies indicate active signaling in prostate cancer and CRPC by several kinases that might represent viable therapeutic targets, such as YAP1 and PAK2." (PMID 34638309, 2021). "The rapid decline in PSA levels may indicate downregulation of PSA expression in hormone-sensitive prostate cancer cells, which are regulated by androgen via the androgen receptor pathway." (PMID 34484340, 2021). "Prostate cancer (PCa) shows strong dependence on the androgen receptor (AR) pathway." (PMID 34417456, 2021). "Previous studies have indicated that PC3 cells (PTEN -/-, AR -/-) are sensitive to PD, suggesting that it may also be a useful treatment for castration-resistance prostate cancer." (PMID 34026624, 2021). "However, in androgen-independent C4-2 prostate cancer cells, the ciglitazone-induced regulation of AR is PPAR-γ-dependent." (PMID 34631571, 2021). "The heterogenous nature of prostate cancer means that different AR may be detected in the tissue of a single patient." (PMID 34204596, 2021).
prostate carcinoma (continued). "The participation of these environmental ligands, as well as individual mutations or expression levels of steroidogenic genes, may explain the inter-individual variability seen in the AR activity related to prostate cancer and other pathologies." (PMID 33919565, 2021). "Manipulation of the AR signalling axis alters the protein cargo in S‐EVs in LNCaP prostate cancer cells, and that the tetraspanin CD9 has been shown to be significantly more abundant in EVs from DHT‐treated cells when comparison with other S‐EVs markers including: TSG101, Alix, CD63 and CD81." (PMID 34434533, 2021). "The activated AR translocates to the nucleus and activates genes related to survival, growth and proliferation which subsequently promote invasive and metastatic behavior in prostate cancer." (PMID 33418978, 2021). "This potential alternative mechanism of Abiraterone has wider implications, being not only a promising drug for AR-insensitive prostate cancer but Abiraterone may also prove to be beneficial in other malignancies apart from PC." (PMID 34367984, 2021). "Furthermore, RSV seems to have a phytoestrogen activity in the androgen receptor (AR) by inhibiting its dimerization and its IL-6 induced transcriptional activity in prostate cancer cells." (PMID 33923359, 2021). "AR is a targetable molecule, widely used in the treatment of prostatic cancer." (PMID 33534004, 2021). "Androgen receptor is the driving force of prostate cancer growth." (PMID 34570813, 2021). "Since HIP1 has a defined positive role to activate AR signaling pathway, the PCAL7‐HIP1 interaction may indirectly augment AR signaling and create a novel positive feedback loop in AR positive or dependent prostate cancer." (PMID 33219721, 2021). "The AR inhibitor enzalutamide is successfully used for the treatment of prostate cancer." (PMID 34211036, 2021). "Interestingly, in primary prostate cancers of different patients, AR chromatin interactions have been shown to be highly variable, suggesting a high level of cistrome heterogeneity in primary disease." (PMID 33576154, 2021). "Therefore, we pursued gene targets occupied by MED19 and AR with an established connection to AR, preferably AR target genes, and known to play a role in prostate cancer proliferation." (PMID 33513133, 2021). "The VHL-based PROTAC named ARD-266 can also target AR for degradation in prostate cancer." (PMID 35006464, 2021). "Galiellalactone also decreased the expression of AR-target genes in explants from benign and malignant prostate models, thus confirming the importance of inhibition of multiple signaling pathways in clinical prostate cancer." (PMID 34204596, 2021). "Therefore, HDAC inhibitors (Jazz90 and Jazz167) were examined in AR-null prostate cancer cell lines (PC3 and DU145)." (PMID 33572730, 2021). "The gene AR is one of the most important genes in prostate cancer related genes." (PMID 34054930, 2021). "HTS2 was applied to identify drugs that block the expression of signature genes regulated by AR in prostate cancer cells, which indicates that this candidate drug may inhibit the AR pathway." (PMID 34660328, 2021). "Such examples include the use of small molecules, such as Comp 5, that induces SIRT1 catalytic activity, resulting in the deacetylation of H3 in glioma or using HAT inhibitors such as CCS1357 for targeting P300/CBP in prostate cancer, leading to the downregulation of AR and MYC." (PMID 34298745, 2021). "However, research has demonstrated that, besides targeting Raf and vascular endothelial growth factor receptor (VEGFR), sorafenib also inhibits the AR and Akt in prostate cancer." (PMID 34026624, 2021). "In animal studies, HRR genes are shown to interact with androgen receptor signaling, which regulates DNA repair in prostate cancer, suggesting that a combination of PARP inhibitors and ARAT may be more effective in patients with HRR mutations." (PMID 33754187, 2021).
prostate carcinoma (continued). "Multiple oncogenes and tumor suppressor genes have been linked with lineage switching from AR-positive to AR-negative prostate cancer." (PMID 33420371, 2021). "Quinazoline-based compounds developed after the pharmacological optimization of α1-adrenoceptor antagonists cause phenotypic reversion of EMT to MET and induce anoikis towards overcoming resistance to AR antiandrogens in pre-clinical models of advanced prostate cancer." (PMID 33672595, 2021). "Androgen receptor (AR) overexpression may lead to androgen resistance and the development of incurable prostate cancer." (PMID 34660328, 2021). "Early use of more intensive therapies targeting androgen receptor and other oncogenic drivers in treatment-naïve primary prostate cancer (PC) may be more effective than that in advanced mCRPC." (PMID 34568716, 2021). "In our prostate cancer patient cohort, we showed that the protein expression of IRE1α, IL-6, and AR correlated in prostate cancer tissues, which may confirm the existence of IRE1α/IL-6/AR positive feedback loop in prostate cancer tissues." (PMID 34295814, 2021). "In addition, signaling proteins of the MAP kinase network are known to be involved in the reactivation of androgen receptor function in prostate carcinoma cells in a cross talk manner." (PMID 34321039, 2021). "The confirmation of this experimental study will provide a complementary treatment for prostate cancer in addition to potential therapy, anti-AR therapy, chemotherapy, and other conventional treatment methods, and provide some research ideas and basis for the mechanism of the drug." (PMID 35342388, 2021). "In prostate cancer, a crosstalk with the AR pathway has been demonstrated, which may participate in resistance to castration and escape from hormone therapy." (PMID 35011901, 2021). "In prostate cancer, different genomic rearrangements can occur, such as the most common fusion of androgen receptor TMPRSS2 with ERG. miR-204 is a TMPRSS2/ERG oncofusion negative regulator and can act as a tumor suppressor or oncomiR, regulating the genes under androgen receptor control." (PMID 34204705, 2021). "Furthermore, analysis of prostate cancer gene expression datasets showed that there was a significant positive correlation between the expression levels of the AR target gene and IRE1α-related gene expression." (PMID 34295814, 2021). "The expression of FOXA1 was observed to cooperate and imbalance the AR cistrome in regulating AR signaling in prostate cancer cells, which may form a mechanism compensating for the functional defects of AR, even in PBMCs with a low abundance of AR expression." (PMID 34867780, 2021). "Similarly, among the therapies for prostate cancer, the use of androgen receptor antagonists or modulators is prominent in the treatment of this pathology, but unfortunately, many cancers develop drug resistance, hampering the effectiveness of the therapy." (PMID 33669559, 2021). "However, if resistance pathways are repressed with simvastatin and an AKR1C3 inhibitor, this can likely overcome resistances to AR targeted therapies in prostate cancer." (PMID 33808627, 2021). "Since the actions of androgens and androgen receptor (AR) are among the drivers of prostate cancer, one of the therapeutical approaches to treat prostate cancer is androgen deprivation therapy (ADT) and the downregulation of AR signaling, which is accomplished by various strategies." (PMID 33572160, 2021). "Moreover, overexpression of miR-212 can restrain the castration resistance of prostate cancer by inhibiting hnRNPH1 and in turn reducing the expression of the AR and AR-v724." (PMID 34103477, 2021). "Interestingly, bombesin promotes the proliferation of neuroblastoma and pancreatic cancer cells and augments the activity of androgen receptor (AR), a critical receptor in the progression of prostate cancer." (PMID 33807481, 2021).